PON1 (paraoxonase 1)
Diseases named in the same sentence as PON1 in open-access papers (continued):
Sharing a sentence is not in itself a finding about the gene and the disease.
diabetes (continued). "Therefore more extensive studies have to be carried out on PON1 enzyme for the management of diabetes." (PMID 23497651, 2012). "PON1 enzymatic activity has been shown to decrease in patients with diabetes." (PMID 23497651, 2012). "The role of PON1 activity in HDL in diabetes has become an important concern." (PMID 18036220, 2007). "Reduced PON1 activity has been described in a wide range of inflammatory and oxidative-stress–related conditions, including atherosclerotic cardiovascular disease, diabetes mellitus, chronic obstructive pulmonary disease, rheumatoid arthritis, and other autoimmune disorders." (PMID 41601643, 2026). "This may suggest that PON1 levels could be influenced by diabetes-related oxidative stress." (PMID 40342642, 2025). "Diabetes status was included due to its significant prevalence differences across groups (p < 0.01) and its established role as a comorbidity that exacerbates HF through metabolic and vascular pathways, which may intersect with PON1’s antioxidant functions." (PMID 40422267, 2025). "PON1 is capable of hydrolyzing a wide spectrum of substrates including oxidized lipids and is thought to play a role in the development of a large variety of diseases with an inflammatory component, including heart disease, diabetes, rheumatic diseases, neurological diseases and cancer." (PMID 36670930, 2022). "Moreover, PON1 inversely correlated with diabetes duration in T1DM (P < 0.01) and T2DM (P < 0.05)." (PMID 31372141, 2019). "In summary, this study identifies glycated PON1 as a novel risk factor to diabetic vascular complications and uncovers the mechanism by how gly-PON1 induces endothelial dysfunction via ER stress, which is mediated by superoxide/SERCA oxidation/Ca2+ axis in diabetes." (PMID 28374834, 2017). "Thus, in this group of KTR subjects, diabetes was a limited determinant of PON1 status." (PMID 22701797, 2012). "Among these, metabolic diseases such as diabetes mellitus, cardiovascular diseases, and inflammation are the most studied, since they are all characterized by the release of oxidative compounds of different origin that may lead to the consumption of antioxidant molecules such as PON-1." (PMID 41295705, 2025). "Significant differences between the groups were observed for age (p < 0.01), BMI (p = 0.015), the presence of diabetes (p < 0.01), GLS (p = 0.01), LAS (p < 0.01), LVEF (p < 0.01), TETRA (p < 0.01), and PON1 (p < 0.01)]." (PMID 40422267, 2025). "In the present study, PON1 and ARES levels were similarly reduced in diabetic rats; however, treatment with CAR reversed this diabetes-induced decline." (PMID 41516168, 2025). "PON1 binds with HDL (high-density lipoprotein), and high serum levels lead to a protective state against dyslipidemia, cardiovascular diseases, diabetes, stroke, nonalcoholic fatty liver disease, and many others." (PMID 38474211, 2024). "In diabetes mellitus, a high plasma CRP is related to low activity of PON1, independently of pro- and anti-inflammatory adipokines." (PMID 37372026, 2023). "When significant focus was placed on the effect of pomegranate on oxidative stress in rodent models of diabetes, a few markers that were considered included MDA, SOD, CAT, TBARS, GSH, GPx, TAC/AOC, ROS, PON1, FFA, and lipid peroxidation." (PMID 37627561, 2023). "For instance, oral administration of 0.35 mmol of pomegranate for four months significantly increased PON1 gene expression (p < 0.05) and its activity in STZ-induced diabetes in mice fed an HFD." (PMID 37627561, 2023). "Low concentrations of PON1 in HDL from patients with type 1 diabetes mellitus were associated with both albuminuria and coronary artery calcification, suggesting that those alterations in HDL may contribute to the association of albuminuria with CVD risk in type 1 diabetes mellitus." (PMID 34065648, 2021).
diabetes (continued). "This study aimed to investigate the ameliorative effects of citral on selected oxidative parameters and the gene expression of paraoxonase 1 (PON1) and endothelial nitric oxide synthase (eNOS) in a rat model of streptozotocin (STZ)-induced diabetes mellitus." (PMID 34777519, 2021). "Among these, Paraoxonase-1 (PON1), AMP deaminase-1 (AMPD1) and Annexin 1 (ANXA1) are involved in diabetes or GDM." (PMID 34416903, 2021). "Accordingly, we aimed to evaluate the effects of citral on the activities of PON1 and eNOS and on some oxidative stress parameters in serum of rats with streptozotocin (STZ)-induced diabetes mellitus." (PMID 34777519, 2021). "A potentially important finding of our study is demonstrating significantly lower PON1 serum activity in patients with CHD and diabetes mellitus in comparison with normoglycemic patients with CHD." (PMID 30935088, 2019). "In our study, we found significant correlation of PON1 arylesterase activity and HDL-C level and significantly lower PON1 paraoxonase activity in patients with diabetes and positive family history." (PMID 30935088, 2019). "The serum PON1 activity was significantly decreased in the CAD group, the multiple coronary stenosis subgroup, and the diabetes mellitus subgroup compared with each control group." (PMID 28038449, 2017). "It was reported that, related to ROS attack, PON1 and ARE enzyme levels and/or activity were decreased in states of high oxidative stress like diabetes, coronary artery disease, and dyslipidemia." (PMID 25431786, 2014). "At present, most studies have consistently demonstrated reduced PON1 activity in individuals with type 2 diabetes mellitus and/or metabolic syndrome, regardless of the specific substrate used to perform the assessment." (PMID 38136158, 2023). "PON1 activity was lower in 70 participants with T1D in comparison to 30 individuals without diabetes, while it was alike in another study that included smaller groups." (PMID 38247481, 2023). "The interplay between obesity, type 2 diabetes mellitus, and metabolic syndrome is complex, and its influence on PON1 levels has not yet been defined." (PMID 38136158, 2023). "In our study, significantly lower concentrations of PON-1 were observed in patients with diabetes than those without the disease." (PMID 36463116, 2022). "In CAD patients, the PON-1 arylesterase activity was significantly higher among CAD patients without diabetes mellitus (DM) compared to those with diabetes (SMD: 0.235, 95% CI: 0.014 to 0.456, p = 0.03, I2 = 0%)." (PMID 35308142, 2022). "Likewise, our findings showed that the serum levels of PON1 and TAC decreased after the induction of diabetes in rats." (PMID 34777519, 2021). "PON1 was reduced in patients than controls (P < 0.01), in addition PON1 was lower in T1DM than T2DM (P < 0.01), moreover, FBG, HbA1c and lipids was higher in diabetes than controls (P < 0.05)." (PMID 31372141, 2019). "We discovered a significant negative correlation between diabetes mellitus and PON1 paraoxonase activity (R = −0.264, p = 0.026)." (PMID 30935088, 2019). "Currently, a lot of attention is paid to possible relationships of PON1 activity and diabetes, but results are not univocal." (PMID 30935088, 2019). "After 50 days of diabetes, there was clear evidence for oxidative stress in DYOG rats; compared with NYOG rats, the plasma levels of TBARS and ox-LDL were increased, whereas the PON1 activity was decreased." (PMID 28333071, 2017). "It is therefore possible that the increased in vivo glycation of PON1 leads to its glyoxidation and reduction of activity, and is responsible for the derangement of membrane hydroperoxide metabolism found in HDL from people with diabetes." (PMID 28374834, 2017). "Paraoxonase-1 (PON1) has obtained during the last years much interest in clinical and epidemiological research focusing on its protective role in vascular disease diabetes and end-stage renal disease." (PMID 22584062, 2012).
diabetes (continued). "Participants with diabetes had a lower mean PON1 activity than did those without the disease (p = 0.017)." (PMID 21543280, 2011). "The serum homocysteine level and PON1 activity in the DPR group sera were affected by STZ-induced diabetes, which was not the case in the DC, DWR and DBR groups (p < 0.001, Tukey's test)." (PMID 18036220, 2007). "Dr. Vaisar Tomas discovered that elevated concentrations of M-HDL subclass, as well as the abundance PON1 in HDL could protect diabetes patients from vascular complications (independent of HDL-C)." (PMID 37386457, 2023). "However, the interaction between diabetes and gender they reported was not the same as we observed, because diabetes appeared to have a much larger effect on PON-1 in diabetic women." (PMID 35125112, 2022). "Similarly, PON-1 activity has been observed to be decreased in subjects with diabetes but not in those with pre-diabetes or a new diagnosis of diabetes." (PMID 30884808, 2019). "The PON1 polymorphism did not modulate the risk of CAD in response to exposure to other traditional risk factors such as the following: male gender, hypertension, diabetes mellitus, overweight/obesity, and plasma lipid abnormalities." (PMID 29118461, 2017). "PON1 gene status may play a role in obesity independent of genetic ancestry and lead to insulin resistance and diabetes." (PMID 33889422, 2015). "Further, there was a difference in PON1 mass, but not arylesterase activity by diabetes status." (PMID 22701797, 2012). "Furthermore, the effect of the interaction term diabetes*Q192 was significant for the prediction of PON1 concentration (interaction P = 0.007), but not for PONase, suggesting that the effect of the variant on PON1 concentration was more important in participants with diabetes." (PMID 25477710, 2014). "Another publication, which investigated PON-1 activity rather than its concentration, likewise reported a decrease in the activity of PON-1 in patients with diabetes, irrespective of the presence or absence of IHD." (PMID 36463116, 2022). "Sex, age, BMI, and diabetes altogether explained 29.2% of CIMT, with no further improvement from adding PON1 and/or antioxidant status indices." (PMID 24799979, 2014). "Moreover, PON1 55 M+ and M‒ carriers did not significantly correlate with history of CHD, diabetes mellitus, arterial hypertension, smoking habits, hypercholesterolemia, and low HDL-cholesterol (data not shown)." (PMID 22536511, 2012). "The lack of ability to detect any significant difference in PON-1 activity between T2DM and controls in HDL subfractions could be due to several factors, such as limited sample size, the age of onset, and duration of diabetes." (PMID 28596970, 2017).
coronary artery disease (108 papers, 2006 to 2025). "Decreased PON1 activity has been associated with the development of several diseases, such as coronary artery disease, lung cancer, obstructive sleep apnea, and chronic obstructive pulmonary disease." (PMID 39684469, 2024). "One study found a positive association between low PON-1 activity and the severity of coronary artery disease, particularly in smokers and diabetic patients." (PMID 39336967, 2024). "It has also been claimed that PON1 polymorphisms (C-108T, M55L, G-162A, R-160G,) are associated with coronary artery disease." (PMID 39684839, 2024). "Since several studies have explored the positive association between these two PON1 variants and the susceptibility to coronary artery diseases." (PMID 38173046, 2024). "Previous studies suggest associations between PON1 gene polymorphisms and various forms of cardiovascular disease, such as coronary artery disease, myocardial infarction and ischemic stroke, in different populations." (PMID 39062650, 2024). "Some human epidemiological studies have revealed an association between low Pon1 levels and an increased risk for coronary artery disease." (PMID 37146172, 2023). "The results of some studies indicate that not only HDL itself but also PON1 is an independent risk factor for coronary artery disease (CAD)." (PMID 37372026, 2023). "Low levels of PON1 lead to increased endothelial damage and, consequently, increased risk of coronary disease." (PMID 37948561, 2023). "Some prospective studies such as the Caerphilly Prospective Study, and a study conducted by Bhattacharyya show that not only HDL itself but also PON1 is an independent risk factor for coronary artery disease." (PMID 35889799, 2022). "The PON1-192Q and the PON1-55M isotypes were correlated with a bigger ischemic heart disease mortality risk, with an OR of 1.71 (1.0–2.8 95% CI, p = 0.03), and an OR of 1.56 (1.1–2.3 95% CI, p = 0.03), respectively." (PMID 36118876, 2022). "Some studies have associated low baseline PON1 activity with increased severity of coronary artery disease, while other studies report an association between high baseline PON1 activity and coronary artery disease severity." (PMID 33779078, 2021). "Recently, PON1 genetic polymorphism and activity were linked to coronary heart disease in aged patients with confirmed DM; thus, PON1 can be considered as an additional diagnostic factor to evaluate cardiovascular risk." (PMID 33923295, 2021). "Decreased PON-1 activity increases proinflammatory and proatherogenic responses and is related to risk factor for coronary artery disease." (PMID 33936387, 2021). "Low serum PON-1 activity is associated with hyperlipidemia, type 1 DM, coronary artery disease, chronic kidney failure, rheumatoid arthritis, metabolic syndrome, uremia, and thyroid dysfunction." (PMID 32267365, 2020). "Among Japanese type 2 diabetes patients, carriers of the polymorphic PON1 rs662 allele were at increased risk for developing coronary artery disease." (PMID 33138337, 2020). "The G allele (rs662) in PON-1 gene was shown to be a risk factor for the development of arterial coronary disease in the Chinese population." (PMID 31052559, 2019). "The GG and AG genotype and G allele of PON-2 (148 A/G) was associated with decrease in PON-1 activity and decrease of coronary heart disease in a Chinese population." (PMID 31052559, 2019). "Results of other studies indicate that lower PON1 paraoxonase and arylesterase activities are associated with severity of lesions of coronary arteries in patients with coronary artery disease." (PMID 30935088, 2019). "Our previous study has reported that lower plasma PON1 activity is associated with increased atherosclerotic lesions in apoE−/− mice and in coronary artery disease (CAD) patients." (PMID 29879989, 2018).
coronary artery disease (continued). "Several types of evidence suggest that low levels of PON1 protein raise the risk of development of premature atherosclerosis and low activity of PON1 is a strong independent risk factor for coronary heart disease." (PMID 28376720, 2017). "rs662 and rs854560 are single nucleotide polymorphisms (SNPs) associated with PON1 activity and 10-year cardiovascular mortality of patients with stable coronary artery disease." (PMID 25155309, 2016). "What is more, the evaluation of PON1 activity demonstrated its decrease was a risk factor associated with increased coronary heart disease susceptibility." (PMID 27437027, 2016). "The results of Koda and colleagues suggest that some differences in the estimates of risk for coronary heart disease can be explained by population differences in haplotype frequencies of the PON1 haplotypes." (PMID 27877192, 2016). "The PON1-192 polymorphism is associated with diminished PON1 concentrations and an increased risk for coronary heart disease in RR-allele subjects." (PMID 26024295, 2015). "ADP induced platelet aggregation level by CYP2C19*2, *3 and PON1 Q192R polymorphisms in clopidogrel treated patients with coronary artery disease." (PMID 25329996, 2014). "Many studies have reported the association between PON1 Q192R polymorphism and coronary artery disease (CAD) with mixed results." (PMID 25329996, 2014). "Studies have shown increased risk of coronary artery disease, carotid atherosclerosis and stroke in patients with low paraoxonase activity PON1 and 2 alleles." (PMID 24816800, 2014). "The association between PON-1 Q192R genotypes and clinical outcome in coronary artery disease (CAD)-patients has been investigated in a couple of aspects." (PMID 23418418, 2013). "Epidemiological evidence demonstrates that low PON1 activity is associated with increased risk of cardiovascular events and cardiovascular disease and is an independent risk factor for coronary artery disease." (PMID 22548179, 2012). "The polymorphisms of PON1 gene are known to affect the PON1 activity and thereby coronary artery disease (CAD) risk." (PMID 21629682, 2011). "Risk of future coronary artery disease by quartiles of PON1 activity and by quartiles of PON-1 activity adjusted for PON1-192 genotype." (PMID 19710913, 2009). "A coding region polymorphism (Q192R) of the human PON1 gene and low serum PON1 activity levels were both associated with increased incidence of coronary heart disease." (PMID 16882531, 2006). "Several studies were performed with the aim to prove whether individuals with the isoenzyme PON1 192R are more susceptible for coronary artery disease that persons with the PON1 192Q form." (PMID 30935088, 2019). "In addition, PON1 arylesterase/paraoxonase activities have been shown to be inversely correlated to the risk of coronary heart diseases and hypercholesterolemia." (PMID 30044465, 2018). "A meta-analysis documented that the Q192R polymorphism is the sole genetic variant in the PON1 gene to show a highly significant, albeit small (7% per R allele), risk for coronary heart disease and another independent meta-analysis estimated a 10% risk excess per R allele for the same outcome." (PMID 27313824, 2016). "The results suggest that PON-1 activity and 8-iso-PGF2α concentration are associated with the presence and extent of coronary stenosis and may be considered additional markers of coronary artery disease." (PMID 26697134, 2015). "Although the present study excluded patients with documented coronary artery disease, the low levels of PON-1 may be an indicator of increased cardiovascular risk and a symptom of subclinical coronary artery disease in the patient group with MeS." (PMID 25530760, 2014). "In a previous work, we showed for the first time that these novel PON1 activity assays may be associated with coronary artery disease (CAD)." (PMID 21960992, 2012).